SERPINB1 (serpin family B member 1)
Description:
Neutrophil serine protease inhibitor that plays an essential role in the regulation of the innate immune response, inflammation and cellular homeostasis. Acts primarily to protect the cell from proteases released in the cytoplasm during stress or infection. These proteases are important in killing microbes but when released from granules, these potent enzymes also destroy host proteins and contribute to mortality. Regulates the activity of the neutrophil proteases elastase, cathepsin G, proteinase-3, chymase, chymotrypsin, and kallikrein-3. Also acts as a potent intracellular inhibitor of GZMH by directly blocking its proteolytic activity. During inflammation, limits the activity of inflammatory caspases CASP1, CASP4 and CASP5 by suppressing their caspase-recruitment domain (CARD) oligomerization and enzymatic activation. When secreted, promotes the proliferation of beta-cells via its protease inhibitory function.
Synonyms: LEI; EI; M/NEI; PI-2; ELANH2; MNEI; PI2; HEL-S-27; HEL57
Tractability: Antibody: UniProt places it where antibodies can reach, with high confidence; its Gene Ontology location is reachable by antibodies, with high confidence. PROTAC: ubiquitination databases record sites on it; its protein half-life has been measured.
Gene: Protein-coding gene on chromosome 6 (2,832,332 to 2,842,001, reverse strand). Ensembl gene ENSG00000021355.
Subcellular location: Secreted; Cytoplasm; Cytolytic granule; Early endosome
Subcellular location (Human Protein Atlas): Cytoplasmic bodies; Predicted to be secreted
Pathways (Reactome):
Immune System: CASP4 inflammasome assembly; Neutrophil degranulation
Gene Ontology:
Molecular function: peptidase inhibitor activity; protein binding; serine-type endopeptidase inhibitor activity
Biological process: negative regulation of cell migration; negative regulation of endopeptidase activity; negative regulation of interleukin-1 beta production; type B pancreatic cell proliferation; regulation of protein metabolic process
Cellular component: cytolytic granule; cytoplasm; cytoplasmic ribonucleoprotein granule; early endosome; extracellular exosome; extracellular matrix; extracellular region; membrane; cytosol; secretory granule lumen
Genetic constraint (gnomAD): Loss-of-function variants: 22 observed, 24.28 expected, observed/expected ratio (o/e) 0.91, 90% interval 0.65 to 1.29. The upper end of that interval is the gene's LOEUF score, 1.29, which puts it in group 5 of 6, group 1 being the genes least tolerant of losing a copy. Missense variants: 376 observed, 460.23 expected, observed/expected ratio (o/e) 0.82, 90% interval 0.75 to 0.89. Synonymous variants: 171 observed, 179.96 expected, observed/expected ratio (o/e) 0.95, 90% interval 0.84 to 1.08.
Homologues: Orthologues: chimpanzee SERPINB1 (99% identical), macaque SERPINB1 (96% identical), dog SERPINB1 (82% identical), rat Serpinb1a (82% identical), pig SERPINB1 (81% identical), mouse Serpinb1a (80% identical), mouse Serpinb1b (76% identical), rat Serpinb1b (75% identical), mouse Serpinb1c (72% identical), guinea pig SERPINB1 (65% identical), zebrafish serpinb1 (56% identical), zebrafish serpinb1l2 (51% identical). Paralogues in human: SERPINB8 (53% identical), SERPINB6 (52% identical), SERPINB9 (51% identical), SERPINB4 (50% identical), SERPINB3 (50% identical), SERPINB2 (50% identical), SERPINB10 (48% identical), SERPINB13 (48% identical), SERPINB11 (47% identical), SERPINB12 (44% identical), SERPINB7 (40% identical), SERPINB5 (39% identical), and 24 more.
Diseases named in the same sentence as SERPINB1 in open-access papers:
SERPINB1 is named in the same sentence as 72 diseases in open-access papers, as found by Europe PMC text mining. Sharing a sentence is not in itself a finding about the gene and the disease. The quoted sentences say what the papers report.
Insulin resistance (7 papers, 2017 to 2025). Increased resistance towards insulin, that is, diminished effectiveness of insulin in reducing blood glucose levels. "Abnormal serum levels of NRG4, AFM, and SERPINB1, as highly sensitive diagnostic tools, are closely related to insulin resistance in GDM patients." (PMID 36072413, 2022). "In our present study, SerpinB1 was positively associated with insulin sensitivity index and better blood glucose level, and negatively correlated with hyperlipidemia and hyper-concentration of γGTP, which were related to hepatic insulin resistance." (PMID 36331940, 2022). "SerpinB1 was identified as a hepatokine that promoted pancreatic β-cell proliferation to compensate for insulin resistance in the liver-specific insulin receptor knockout mouse." (PMID 36331940, 2022). "Plasma and liver SerpinB1 levels are elevated in mice with insulin resistance and promote β-cell proliferation in human islets." (PMID 36331940, 2022). "Among these hepatocyte-derived factors, serine protease inhibitor B1 (serpinB1; serpin family B member 1) has been identified to play an important role in that process of β-cell compensation in response to insulin resistance." (PMID 32903749, 2020). "SerpinB1 knockout in mouse models of insulin resistance attenuated compensatory β‐cell proliferation." (PMID 28292880, 2017). "This study aims to explore the serum levels of neuregulin 4 (NRG4), afamin (AFM), and serpin family B member 1 (SERPINB1) in gestational diabetes mellitus (GDM) patients and their relationship with insulin resistance." (PMID 36072413, 2022). "However, since in our mouse model of severe insulin resistance induced by GC, an increase in pancreatic beta cell proliferation was observed, it could be interesting to study whether GC can promote hepatic secretion of SERPINB1." (PMID 33435513, 2021). "Recently, it was observed that in response to hepatic insulin resistance (LIRKO mice), hepatic cells secrete a serine proteinase inhibitor, SERPINB1, which stimulates pancreatic beta cell proliferation in mouse and human islets." (PMID 33435513, 2021). "Our results do not support the theory that circulating serpinB1 is a marker of insulin resistance and thus may play a role in compensatory hyperinsulinemia in humans." (PMID 28292880, 2017). "Indeed, in this study, insulin resistance was not severe in T2DM subjects, which may have resulted in relatively low serum SerpinB1 levels compared to those in previous reports in the US." (PMID 36331940, 2022).
glioma (6 papers, 2010 to 2025). A benign or malignant brain and spinal cord tumor that arises from glial cells (astrocytes, oligodendrocytes, ependymal cells). "SERPINB1 levels were found decreased in patients with prostate cancer, glioma, and HCC, favoring migration and invasion, while displaying increased expression in cells and patients with oral cancer, correlating with high motility and cell migration in vitro." (PMID 32183400, 2020). "SerpinB1 is a member of the Serpin family of proteinase inhibitors that protect cells from inflammatory signaling but also regulates cell migration and invasion in gliomas." (PMID 25260591, 2014).
prostate carcinoma (6 papers, 2016 to 2022). A carcinoma that arises from epithelial cells of the prostate gland. "On the contrary, hypermethylation of SERPINB1 promoter resulted in enhanced neutrophil elastase (NE) activity, which was associated with poor outcome in prostate cancer." (PMID 33134164, 2020). "Recently, it was revealed that EZH2, through H3K27 methylation, suppressed the expression of SERPINB1, which in turn promoted inflammation-mediated prostate cancer progression." (PMID 32371945, 2020). "Interestingly, endogenous NE inhibitors, like SERPINB1, are down-regulated in early and advanced prostate cancer, which is indicative of another strategy to establish high NE activity in tumours." (PMID 35874783, 2022). "In addition to Rab7, it was revealed that overexpression of serine protease inhibitor B1 (SERPINB1; also known as ILEU) promotes the motility of oral squamous cell carcinoma, but the epigenetic suppression of SERPINB1 predicts a poorer prognosis in prostate cancer patients." (PMID 33888099, 2021).
breast carcinoma (4 papers, 2013 to 2021). "Two studies described SERPINB1 as a dose-dependent potent suppressor of metastasis in terms of invasion and migration in oral squamous cell carcinoma, and in lung and breast cancer, respectively." (PMID 26799424, 2016). "For example, two studies that profiled gene expression in response to 1,25D treatment of breast cancer explants in culture, which were primarily ER+ ductal carcinomas, revealed only four commonly regulated genes (CYP24A1, CLMN, EFTUD1, SERPINB1)." (PMID 34950835, 2021).
diabetes (4 papers, 2017 to 2022). "In this study, we investigated 2 SERPINB1 SNPs, rs114597282 and rs15286, regarding their association with diabetes risk and various anthropometric and biochemical parameters in Egyptian type 2 diabetic patients." (PMID 32903749, 2020). "Just one family has been identified with a possibly damaging SERPINB1 variant associated with diabetes." (PMID 32903749, 2020). "In this study, we assessed two SERPINB1 gene SNPs in control and type 2 DM patients and investigated their association with the risk of diabetes and other anthropometric and biochemical parameters." (PMID 32903749, 2020). "In addition, this study opens the door for further studies to investigate the possible association between other SERPINB1 gene variants and susceptibility for diabetes and/or diabetic complications in different ethnic populations." (PMID 32903749, 2020). "Recently, SERPINB1 has attracted attention in the treatment of diabetes mellitus treatment due to its role in inducing β-cell proliferation." (PMID 36072413, 2022). "However, still the genetic variants of the SERPINB1 gene and their association with diabetes have not been studied." (PMID 32903749, 2020). "Subjects with diabetes often exhibit hyperinsulinemia, glucagon dysregulation, hyperglycemia-induced microinflammation, oxidative stress, endoplasmic reticulum (ER) stress, and/or dyslipidemia, which might regulate the SerpinB1 expression via hepatic regulation of FoxO1." (PMID 36331940, 2022). "Therefore, the correlation between SerpinB1 and insulin sensitivity or β-cell function in this study did not seem to be influenced by the use of anti-diabetes drugs." (PMID 36331940, 2022).
type 2 diabetes (4 papers, 2017 to 2022). "A small sample size of the study showed that elevated serum level of SERPINB1 was revealed in the patients with type 2 diabetes compared to the healthy controls, and SERPINB1 was significantly negatively correlated with serum low-density lipoprotein cholesterol." (PMID 36072413, 2022). "This indicates that type 2 diabetic patients' carriers of the AA genotype may potentially have better control over their blood glucose levels and better β-cell function than other genotypes of this SERPINB1 SNP." (PMID 32903749, 2020). "We measured serum SerpinB1 levels in Japanese subjects with or without type 2 diabetes (T2DM)." (PMID 36331940, 2022).
lung carcinoma (3 papers, 2016 to 2021). "An explorative two-way ANOVA analysis and planned post-hoc contrast analysis of the 566 investigated platelet proteins revealed that SERPINB1 (leukocyte elastase inhibitor) had the strongest dependency (p = 0.028) on lung cancer and mortality." (PMID 34066760, 2021). "SERPINB1 protein has recently been identified by gel electrophoresis and subsequent mass spectrometry to be differentially expressed in gastric and lung carcinoma, respectively, as compared to healthy tissues." (PMID 26799424, 2016). "The platelet SERPINB1 level of this deceased patient stayed decreased (SA = 1.10) after three months compared to the corresponding baseline value (SA = 1.17) and the mean baseline value of all deceased patients (SAmean = 1.10; n = 11) with lung cancer." (PMID 34066760, 2021). "The quantitative representation of the actual group effects separately for cancer type and mortality showed that SERPINB1 was significantly decreased in deceased compared to surviving patients with lung cancer (FC = 0.82; p = 0.03) and healthy controls (FC = 0.83; p = 0.003)." (PMID 34066760, 2021). "Chou and others have shown that SERPINB1 may play a role as a tumor suppressor in breast and lung cancers." (PMID 29207610, 2017). "Finally, using an exploratory two-way ANOVA that included both cancer type and patient mortality, we found significantly reduced SERPINB1 levels in non-surviving lung cancer patients in the platelet proteome data of the current 2D-DIGE study, but not in brain cancer." (PMID 34066760, 2021).
oral cancer (3 papers, 2016 to 2021). "For example, azurocidin seems to have a protective role in alveolar bone loss during the early stages of periodontitis whereas SERPINB1 positively correlated with cell migration and oral cancer metastasis." (PMID 34064456, 2021).
oral squamous cell carcinoma (3 papers, 2016 to 2022). "However, high expression of SERPINB1 in clinicopathologically invasive oral squamous cell carcinoma but not in normal oral mucosa (P < 0.01) was found by Tseng MY." (PMID 36085041, 2022).
acute myocardial infarction (2 papers, 2022 to 2025). Necrosis of the myocardium, as a result of interruption of the blood supply to the area. "The purpose of this study was to explore the effect of SERPINB1 on acute myocardial infarction (AMI)." (PMID 35291946, 2022).
amoebiasis (2 papers, 2017 to 2022). "Five infectious diseases were overrepresented, four of them being of viral origin: HTLV-I infection, hepatitis C, hepatitis B and influenza A. The up-regulated SERPINB1 gene was annotated to, inter alia, the overrepresented amoebiasis KEGG pathway from fourth IC." (PMID 29028836, 2017). "For example, among amoebiasis pathway-related proteins, integrin beta-2 (ITGB2), heat shock protein beta-1 (HSPB1), LCN2, leukocyte elastase inhibitor (SERPINB1), laminin subunit alpha-4 (LAMA4), and fibronectin (FN1) have been found to be correlated with immunity." (PMID 36387401, 2022).
colorectal cancer (2 papers, 2022 to 2024). A primary or metastatic malignant neoplasm that affects the colon or rectum. "Proteinase inhibitor SERPINB1 has not been widely explored in relation to intestinal or colorectal cancer, but proteomics results indicate that SERPINB1 is downregulated in skin and prostate tumor tissues." (PMID 38732562, 2024).
cystic fibrosis (2 papers, 2023 to 2025). Autosomal recessive disorder caused by pathogenic variants in the CFTR gene (cystic fibrosis transmembrane conductance regulator), which encodes a chloride and bicarbonate channel expressed in epithelial cells, and follow the diagnosis criteria. "SERPINB1, a proteinase/elastase inhibitor, protects against Pseudomonas aeruginosa lung infection in mice and may serve as a biomarker for cystic fibrosis-related inflammation, with its role in asthma yet to be explored." (PMID 38062491, 2023). "The overexpression of cathepsin G and underexpression of SERPINB1 and SLPI have been reported in muco-obstructive respiratory diseases such as cystic fibrosis and COPD." (PMID 40650225, 2025).
diabetic nephropathy (2 papers, 2021 to 2025). "Taken together, the results showed that FoxO1/SERPINB1 ameliorates ROS production—induced oxidative stress in diabetic nephropathy vivo or vitro model." (PMID 33473269, 2021). "The present study provides some ideas for FoxO1/SERPINB1 that can relieve the symptoms of ROS production in diabetic nephropathy." (PMID 33473269, 2021). "The detailed mechanism by which FoxO1/SERPINB1 ameliorates ROS production in diabetic nephropathy needs further investigation." (PMID 33473269, 2021). "This study reported that FoxO1 regulated SERPINB1 to reduce ROS production in diabetic nephropathy." (PMID 33473269, 2021). "Based on these data, serpinB1 may protect renal cells against ROS production in diabetic nephropathy." (PMID 33473269, 2021). "Furthermore, FOXO mediated by SERPINB1 decreases ROS production and MDA levels in a diabetic nephropathy in vitro model." (PMID 40649025, 2025).
hepatitis C (2 papers, 2017 to 2020). "SERPINB1 acts in host-pathogenic interactions and possesses some antiviral activity across infections of rhabdovirus, hepatitis C, and influenza A." (PMID 33301474, 2020).
hepatocellular carcinoma (2 papers, 2014 to 2024). A malignant tumor that arises from hepatocytes. "Decreased expression of hepatic SERPINB1 has been associated with tumour invasiveness and poor prognosis in humans with hepatocellular carcinoma." (PMID 38535834, 2024). "SERPINB1 (serine protease inhibitor, clade B, member 1) has been shown to be downregulated in hepatocellular carcinoma and is correlatively related with cancer metastasis and intravasation." (PMID 25254241, 2014).
inflammatory bowel disease (2 papers, 2022). A spectrum of small and large bowel inflammatory diseases of unknown etiology. "A related animal study has suggested that SERPINB1 was involved in intestinal barrier dysfunction by disrupting tight junction, and thus could play an important role in the pathogenesis of inflammatory bowel disease." (PMID 35804609, 2022).
melanoma (2 papers, 2016 to 2020). A malignant, usually aggressive tumor composed of atypical, neoplastic melanocytes. "First, we transduced three melanoma cell lines with two different inducible SERPINB1-specific shRNA vectors." (PMID 26799424, 2016). "Importantly, SERPINB1 levels were shown to predict the outcome of cisplatin-based chemotherapies in melanoma and the value of this transcript/protein as surrogate marker for CCA should be evaluated in the future." (PMID 32183400, 2020). "Notably, melanoma cell lines under long-term treatment with increasing doses of cisplatin revealed a reduction of SERPINB1 expression." (PMID 26799424, 2016). "This advantage emphasizes SERPINB1 as a useful marker predicting the outcome of cisplatin-based chemotherapies, and may help to personalize chemotherapy of melanoma." (PMID 26799424, 2016). "Consequently, we determined the effect of SERPINB1 expression on cisplatin sensitivity in melanoma cells." (PMID 26799424, 2016). "However, knockdown of SERPINB1 expression by shRNA did not influence cisplatin sensitivity in melanoma cell lines." (PMID 26799424, 2016). "We conclude, that SERPINB1 expression, although not functionally involved, is predictive for the outcome of cisplatin-based chemotherapy in melanoma, and thus may be useful to personalize melanoma chemotherapy." (PMID 26799424, 2016).
Sepsis (2 papers, 2021 to 2023). Sepsis is defined as life-threatening organ dysfunction caused by a dysregulated host response to infection. "The most modulated genes were Granzyme B, Complement Factor B, Complement Component 4 Binding Protein Alpha, IL-12, and SERPINB-1 that were closely related to sepsis-induced immunological process." (PMID 33868226, 2021). "Eight genes (CLEC5A, MALT1, NAIP, NLRC4, SERPINB1, SIRT1, STAT3, and TLR2) related to sepsis diagnosis were screened by multiple machine learning algorithms." (PMID 36817458, 2023).
viral infections (2 papers, 2020 to 2022). "SERPINB1 loss increased the susceptibility of mice to pulmonary bacterial and viral infections." (PMID 36387401, 2022). "Comparative gene expression analysis of the five viral infections (SARS-CoV-2, EBOV, H1N1, MERS-CoV, and SARS-CoV) yielded SERPINB1 as the common response gene among the five infections." (PMID 33301474, 2020).
Alzheimer disease (1 paper, 2025). A progressive, neurodegenerative disease characterized by loss of function and death of nerve cells in several areas of the brain leading to loss of cognitive function such as memory and language. "Although the functions of SERPINB1 in the nervous system have not been extensively studied, SERPINB1 transcripts were found dysregulated in sporadic Creutzfeldt-Jakob disease and Alzheimer’s disease (AD) patients." (PMID 41298695, 2025).